ENSG00000285839 (novel transcript)
Gene: Protein-coding gene on chromosome 1 (52,020,153 to 52,033,350, reverse strand). Ensembl gene ENSG00000285839.
Genetic constraint (gnomAD): Missense variants: 290 observed, 302.91 expected, observed/expected ratio (o/e) 0.96, 90% interval 0.87 to 1.05. Synonymous variants: 118 observed, 134.37 expected, observed/expected ratio (o/e) 0.88, 90% interval 0.75 to 1.02.